MTOR (mechanistic target of rapamycin kinase)
Diseases named in the same sentence as MTOR in open-access papers (continued):
Sharing a sentence is not in itself a finding about the gene and the disease.
cancer (continued). "Despite the well-recognized importance of microRNAs and mTOR in cancer, very few studies have linked microRNAs with mTOR activity." (PMID 24009623, 2013). "One discovery from these works is the intriguing relations between FLCN and the mechanistic target of rapamycin (mTOR), a highly conserved nutrient sensor among eukaryotes whose mutations have been found in certain human diseases including cancer." (PMID 23799055, 2013). "The data indicates that inhibition of ErK/mTOR/Hsp90 can cause apoptosis in cancer cells induced by down-regulation of Slug through changes in the expression of Bim." (PMID 24130883, 2013). "False-positive report probability values for associations between the risk of cancer and the frequency of genotypes of mTOR variants." (PMID 23940798, 2013). "Other cancer pathways including the mTOR pathway have also been implicated in ribosome biogenesis and have been previously shown to be important for promoting transcription of ribosomal RNAs." (PMID 23976967, 2013). "In summary, the present study revealed a new mechanism associated with mTOR inhibition that triggered the impairment of cell proliferation and the induction of the cell death of cancer cells." (PMID 24179542, 2013). "By controlling important downstream targets, mTOR exerts a crucial role in cell fate decisions, so that mTOR signaling dysregulations have been implicated in various forms of human cancer." (PMID 24228033, 2013). "As a result, we conduct this meta-analysis of published prospective trials to determine the incidence and risk of mTOR inhibitors associated FAEs in patients with cancer." (PMID 23785409, 2013). "PA is a necessary co-factor for the activity of diverse proteins, such as Raf family proteins, PKC-ζ, RAB11FIP1, PLC-β, SOS and mTOR, which have been implicated in cancer cell proliferation, survival, and tumorigenesis." (PMID 24205284, 2013). "Studies performed in cancer cells lines implicated the expression of Livin was under the regulation of Catenin/TCF or mTOR pathways which were considered hallmark signaling changes in cancers." (PMID 24295240, 2013). "The pooled RR for FAEs showed that the use of mTOR inhibitors significantly increased risk of developing FAEs in cancer patients with RR of 3.244 (95%CI: 1.214–8.667, p = 0.008) using a fixed-effects model (I2 = 0%, p = 0.912)." (PMID 23785409, 2013). "Many targets of mTOR kinase are overexpressed or mutated in cancer, which correlates with cancer progression, adverse prognosis, and resistance to chemotherapy." (PMID 23667692, 2013). "Although mTor and the mTor pathway are activated in a wide variety of human cancers, being implicated in tumourigenesis, an emerging body of evidence puts the output of mTor signaling in a more context-dependent image." (PMID 24216995, 2013). "AKT/mTOR signaling is known to be important for several hallmark cellular processes that give cancer cells a competitive advantage over that of normal cells." (PMID 22680924, 2012). "The MTOR gene encodes a serine/threonine kinase and its downregulation is associated with extended lifespan in model organisms and elevated mTOR activity has been implicated in different forms of human cancer [reviewed in 53]." (PMID 22247756, 2012). "Rapamycin and rapalogs are being used to treat certain cancers which proliferate in response to mutations in regulatory genes which control the PI3K/PTEN/Akt/mTOR pathway." (PMID 23085539, 2012). "The mTOR pathway is constantly active in cancer cells due to mutations in receptor kinases, Ras, Akt, or loss of tumor suppressors (e.g., PTEN, TSC-2)." (PMID 23565531, 2012). "Metformin LKB1 activation in human cancer cell lines in vitro is associated with inhibition of the mammalian target of rapamycine (mTOR), with subsequent reduced cellular proliferation." (PMID 22421948, 2012). "RTKs are well-known activators of the MAPK/Erk and Akt/mTOR pathways, and mutations of RTKs in cancer lead to constitutive activation of these pathways." (PMID 22839755, 2012).
cancer (continued). "Given the importance of the PI3K/Akt/mTOR pathway in regulating mRNA translation of genes that encode for pro-oncogenic proteins and activated mTORC1 signalling in a high proportion of cancers, these kinases have been actively pursued as oncology drug targets." (PMID 22392765, 2012). "Elucidating the role of AKT/mTOR in metabolism and in hallmark signaling pathways that are aberrantly affected in cancer has provided a solid foundation of discoveries." (PMID 22680924, 2012). "The importance of PI3K/Akt/mTOR signaling in cancer is highlighted by the fact that mutations in the tumor suppressor gene PTEN occur frequently in human tumors, including glioblastoma." (PMID 23056595, 2012). "Activation of the canonical PI3K/AKT/mTOR pathway seems to be associated with resistance to EGFR inhibitor in multiple human cancers." (PMID 22666248, 2012). "Cross-feedback activation of MAPK and AKT pathways is implicated as a resistance mechanism for cancer therapeutic agents targeting either RAF/MEK or PI3K/AKT/mTOR." (PMID 22880048, 2012). "Inappropriate activation of mTOR has been implicated in the pathogenesis of a range of cancers and can account for tumor proliferation and growth." (PMID 24300398, 2012). "Cancer cells harboring a PI3K gain-of-function mutation or a PTEN deletion demonstrate higher PI3K/mTOR pathway activity and greater sensitivity to BEZ235." (PMID 23077520, 2012). "The high frequency of somatic and germline mutations resulting in mTOR pathway activation makes pharmacological inhibition of mTOR a promising therapeutic avenue for a variety of human cancers." (PMID 23155392, 2012). "Given the key role of mTOR in cell growth and metabolism, it is predictable the existence of an association between mTOR pathway activity and pathological states, including cancer." (PMID 22408430, 2012). "The mTOR signaling pathway is critical to cell growth, proliferation, and survival and rapamycin inhibits these hallmark processes of cancer." (PMID 23369283, 2012). "PI3K/Akt/mTOR constitutive activation is linked both to the pathogenesis and to progression of a wide variety of human cancers, including T-ALL." (PMID 22885370, 2012). "Mammalian target of rapamycin (mTOR) is an enzyme in the cellular phosphatidylinositol 3-kinase (PI3 K) pathway commonly associated in human cancer pathogenesis." (PMID 23198184, 2012). "Namely, pharmacological activation or overexpression of AMPK in a variety of cancer cell types caused an mTOR inhibition-associated cell cycle arrest and apoptotic death both in vitro and in vivo." (PMID 22496691, 2012). "Like rapamycin, RAD001 causes Akt activation in human cancer cells including NSCLC cells while inhibiting the mTOR signaling." (PMID 21695126, 2011). "Since the loss of PTEN results in activation of Akt, that in turn up-regulates mTOR activity, cancer cells deficient in PTEN are thought to be major targets of mTOR inhibitors." (PMID 21422497, 2011). "In the previous sections, we have discussed the mechanisms of activation of the Ras/Raf/MEK/ERK and Ras/PI3K/PTEN/Akt/mTOR pathways in human cancers, predominantly by mutational based mechanisms." (PMID 21422497, 2011). "Sirolimus (rapamycin) is of course the archetypal inhibitor of mTOR, which in cancer cells is associated with increased angiogenesis, stimulation of protein synthesis and inhibition of cell death." (PMID 21846376, 2011). "It is important to realize that HEK 293 cell are non-tumorigenic, therefore no corrupted signal transduction by oncogenic mutations via the PI3K/Akt/mTOR pathway was present which supported fast cellular biosynthesis in cancer cells." (PMID 21573193, 2011). "The PI3K/AKT/mTOR signaling pathway contains several such proteins that have been implicated in a number of diseases, including a variety of cancers and some psychiatric disorders." (PMID 21949775, 2011).
cancer (continued). "SNPs in genes belonging to the mTOR pathway have already been studied in relation to cancer risk, with some promising results." (PMID 21373201, 2011). "Cancers containing PIK3CA mutations are often sensitive to the mTOR inhibitor rapamycin and the modified rapamycins (Rapalogs)." (PMID 21411864, 2011). "The anti-cancer effect of β-elemene was associated with inhibition of the PI3K/Akt/mTOR/p70S6K1 signaling pathway, which also led to the activation of a protective autophagy." (PMID 21595977, 2011). "Akt, mTOR and p70S6K activation have been associated with a more severe prognosis in breast and other cancers." (PMID 21730367, 2011). "The pro-senescent phenotype due to overactivation of MAPK and PI3K/mTOR can be linked to hallmarks of cancer such as angiogenesis, apoptosis-avoidance, Warburg effect, invasion and metastasis (I will discuss this in forthcoming reviews)." (PMID 21297220, 2011). "Here to compare cancer with aging, I view oncogenic transformation as (a) activation of growth-promoting pathways such as mTOR and (b) loss of cell cycle control." (PMID 22246147, 2011). "While somatic mutations in the PI3K/AKT/mTOR pathway are common in many types of cancer, inherited variation has also been implicated in cancer and several psychiatric diseases." (PMID 21949775, 2011). "Dysregulation of the mammalian target of rapamycin (mTOR) signaling has been found in many human cancers, particularly those with loss of the tumor suppressor PTEN." (PMID 22039466, 2011). "mTOR, which is constitutively activated in many cancers by deregulated activation of oncogenes or loss of tumor suppressor genes, functions as macromolecular complexes." (PMID 21886838, 2011). "Noteworthy, the activation PI3K/mTOR pathway by mutations is one of the most universal alterations in cancer." (PMID 22267462, 2011). "Second, mTOR overactivation can cause insulin resistance, which in turn leads to a compensatory increase in insulin levels, which can promote cancer." (PMID 22267462, 2011). "Because the number of potential defects that can cause inappropriate activation of mTOR is large and one or the other is common to most cancer cells, blocking their effect at the point of convergence is a rational approach." (PMID 21584218, 2010). "The mTOR signaling cascade has been implicated in membrane traffic and is activated in nearly all human cancers, but clinical response to the mTOR-specific inhibitor rapamycin has been disappointing." (PMID 20495773, 2010). "Signaling through the mTOR pathway has been linked to growth, progression and chemoresistance of several cancers." (PMID 20543980, 2010). "Whereas nutlin-3a causes quiescence in WI-38t and RPE cells, it causes senescence in some cancer cell lines with high mTOR activity." (PMID 21212465, 2010). "Cancer cells commonly have mutations and/or overexpression of several signalling molecules, resulting in the activation of mTOR and its substrates S6K1 and 4E-BP1." (PMID 19127256, 2009). "Our study is the first to show that different localisation of mTOR expression (i.e., cytoplasmic vs nuclear) was associated with different outcomes in patients with cancer." (PMID 19223902, 2009). "In conclusion, mTOR inhibition causes antitumour activity in EGFR-resistant cancer cell lines and xenografts, and this effect seems to be mediated by inhibition of survival signalling pathways and angiogenesis." (PMID 18319715, 2008). "PI3K/AKT/mTOR pathway is often activated in cancer due to genetic alterations of the genes implicated in this pathway." (PMID 18652687, 2008). "Previous studies have implicated the AKT/mTOR pathway in a diverse range of cancers including prostate, lung, pancreas, colon and oesophagus." (PMID 18283322, 2008).
cancer (continued). "A number of studies have tried to find markers for pathway activation, since activation of PI3K/AKT/mTOR pathway is known to be associated with aggressive cancer." (PMID 18652687, 2008). "This places mTOR in a signalling cascade implicated in the abnormal growth and survival of certain cancer cells." (PMID 15365568, 2004). "Experimental studies indicate that cannabinoids inhibit the PI3K/AKT/mTOR pathway, promote reactive oxygen species (ROS)-induced autophagy, and modulate cytokine secretion, mechanisms that underline their dual anti-inflammatory and anti-cancer capabilities." (PMID 41516397, 2026). "EGCG's mTOR inhibitory actions are linked to its anti‐cancer chemo‐preventive properties." (PMID 40717210, 2025). "Furthermore, cancer‐associated fibroblasts (CAFs)‐activated IGF1R/Akt/mTOR/c‐Myc pathway transcriptionally upregulates QSOX2 expression, establishing a QSOX2/mTOR feedback loop that sustains ESCC cell stemness." (PMID 40433832, 2025). "Similarly, heightened mTOR activation has been implicated in several chronic diseases, such as type 2 diabetes, certain cancers, CVD, ADRD, CKD, and NAFLD." (PMID 40574888, 2025). "In fact, under certain pathological conditions, such as cancer-associated cachexia, cirrhosis, and advanced mitochondrial dysfunction, mTOR activity may decline, revealing the context-dependent complexity." (PMID 41469379, 2025). "Additionally, upregulation of NOV is associated with increased mTOR activity, highlighting its role in cancer metabolic reprogramming and proliferation." (PMID 40740240, 2025). "Moreover, PI3K/AKT/mTOR hyperactivation is associated with therapy resistance in various cancers, including parathyroid carcinoma, prostate, breast, colorectal, and lung cancer." (PMID 40722714, 2025). "Modulation of mTOR signaling has also been linked with the cardiotoxicity of anti-cancer therapy." (PMID 41326406, 2025). "Thus, several components of the PI3K/Akt/mTOR pathway frequently show mutations and are activated in cancer." (PMID 40963621, 2025). "In this review, we outline therapeutic targets in PI3K/AKT/MTOR signaling in solid tumors, the current state of using inhibitors of this pathway to treat patients whose cancers possess activating mutations in PIK3CA, AKT1/2, or MTOR, and exciting new inhibitors that are entering clinical trials." (PMID 40564038, 2025). "Since PTEN loss is common in cancer, Notch activation can further increase mTOR pathway activity." (PMID 40003637, 2025). "Evidence from several studies suggests that mTOR inhibitors may be associated with a reduced risk of cancer development." (PMID 41142617, 2025). "The mammalian target of mTOR is a highly conserved serine/threonine protein kinase, and its associated pathway plays a crucial role in regulating various biological processes, including metabolism, cancer, immune function, and aging." (PMID 40959206, 2025). "Notably, GFPT1 has been implicated in interacting with PI3K/AKT/mTOR signaling, to impact the metabolic reprogramming associated with cancer as well as diabetic and cardiac diseases." (PMID 40830088, 2025).
cancer (continued). "Given that PTX is a DNA damage inducer and the PTEN/AKT/mTOR pathway is associated with its anti-proliferative (pro-apoptotic) role in cancer cells, the synergistic effect of ascorbate and PTX on cell proliferation in KLE and Hec-1B cells was evaluated by MTT assay." (PMID 39990670, 2025). "The regulation of DPYSL2 is closely associated with the mTOR signaling pathway, which is known to promote cell growth and division, regulate macrophage polarization, and is widely implicated in cancer biology." (PMID 40487403, 2025). "Moreover, rapamycin, a mTOR inhibitor, pretreatment in cancer cells showed a synergistic effect with LiclA in causing death, cancer prevention, and autophagy induction." (PMID 40717210, 2025). "Increased mTOR activity in aging hypothalamic neurons contributes to age-related obesity, a significant cancer risk factor, while mTOR activation in cancer cells promotes tumor growth and metabolic reprogramming, highlighting its diverse roles in health and disease." (PMID 40046513, 2025). "The mTOR pathway plays a critical role in regulating cell proliferation, growth, migration, and apoptosis, and its dysregulation has been implicated in various cancers, including hematologic malignancies." (PMID 41373823, 2025). "At the molecular level, the platelet-derived growth factor (PDGF), transforming growth factor-beta (TGF-β), and phosphoinositide 3-kinase/protein kinase B/mammalian target of rapamycin (PI3K/AKT/mTOR) axis are heavily implicated in both cancer biology and atherogenesis." (PMID 41007845, 2025). "A study using S. cerevisiae in a mouse model of colorectal tumors to inhibit cancer progression suggests that the downregulation of the Akt/NF-κB and Akt/mTOR signaling pathways may be linked to apoptosis in cancer cells." (PMID 40230717, 2025). "Consequently, it is unsurprising that mutations in components of the mTOR pathway are frequently observed in cancer." (PMID 39940361, 2025). "As evident from our study, the combination therapy of BGT226 and STA9090 could improve the clinical outcomes for patients with cancers harboring mutations in the PI3K/mTOR pathway." (PMID 41282100, 2025). "During PCa, mTOR also directly associates with chromatin in different complexes with transcriptional regulators, including AR, to drive chromatin remodeling and the transcription of genes relevant for cancer progression." (PMID 41009328, 2025). "Importantly, cell growth and survival are regulated by the PI3K/AKT/mTOR pathway, and its dysregulation is often associated with multidrug resistance in cancers." (PMID 40296899, 2025). "Furthermore, large multicentric trials should evaluate tailored immunosuppression management (e.g., dose adjustments, class switches, or mTOR-based strategies) for their effects on both graft function and cancer risk." (PMID 41154407, 2025). "Additionally, evidence suggests an association between mTOR polymorphisms and a predisposition to various cancers." (PMID 39940361, 2025). "The PI3K/AKT/mTOR signaling pathway plays a pivotal role in regulating key cellular processes such as cell survival, apoptosis, and autophagy, and has been strongly implicated in the initiation and advancement of multiple cancer types." (PMID 41408569, 2025). "Additionally, the activation of AMPK and inhibition of mTOR disrupt the abnormal metabolism of tumor cells and induce autophagy, a mechanism often associated with cell death in apoptosis-resistant cancers." (PMID 40572668, 2025). "Clinical studies investigating cancer control have also shown that mTOR inhibition may be promising and cause few adverse effects." (PMID 39851421, 2025).